ILK (integrin linked kinase)
Diseases named in the same sentence as ILK in open-access papers (continued):
Sharing a sentence is not in itself a finding about the gene and the disease.
esophageal squamous cell carcinoma (3 papers, 2020 to 2022). Esophageal squamous cell carcinoma (ESCC) is a type of esophageal carcinoma (EC) that can affect any part of the esophagus, but is usually located in the upper or middle third. "Recent studies have shown that the expression of integrin-linked kinase (ILK) was related to the occurrence, development, and malignant progression of esophageal squamous cell carcinoma (ESCC)." (PMID 35587162, 2022).
exudative vitreoretinopathy (3 papers, 2019 to 2023). Familial exudative vitreoretinopathy (FEVR) is a rare hereditary vitreoretinal disorder characterized by abnormal or incomplete vascularization of the peripheral retina leading to variable clinical manifestations ranging from no effects to minor anomalies, or even retinal detachment with blindness. "Screening genomic DNA samples from exudative vitreoretinopathy patients identifies three distinct mutations in human ILK, which compromise the function of the gene product in vitro." (PMID 31748531, 2019). "Intriguing recent findings in the context of familial exudative vitreoretinopathy (FEVR), a disease involving defective Wnt-β-catenin signaling, further illustrate the strong functional link between ILK and Wnt signaling." (PMID 35804980, 2022).
gastric tumors (3 papers, 2014 to 2019). "In summary, our study systematically evaluated the kinases and associated signaling pathways modulating cell response to FGFR inhibition, and for the first time, demonstrated that targeting ILK would enhance the effectiveness of AZD4547 treatment of gastric tumors with amplifications of FGFR2." (PMID 31076567, 2019). "In human gastric tumors and AGS-derived nodules in BALB/c mice, Ki-67-positive proliferating cells coexpressed ILK as demonstrated by the fluorescence-based immunostaining and AEC-based immunostaining experiments." (PMID 25398317, 2014). "The coexpression of ILK and phosphorylated ERK1/2 (Tyr202/Thr204) was demonstrated in human gastric tumors and AGS-derived nodules in BALB/c mice." (PMID 25398317, 2014).
hyperphosphatemia (3 papers, 2018 to 2022). Abnormally high level of phosphate in the blood. "More recently, it has been shown that hyperphosphatemia, which is associated with mortality in CLDs, induces senescence in myoblasts through overexpression of integrin linked kinase." (PMID 31595206, 2019). "Knocking-down ILK expression increased autophagy and protected cells from senescence induced by hyperphosphatemia." (PMID 30271655, 2018). "However, our results demonstrate that overexpression of ILK induced by hyperphosphatemia leads to cellular senescence." (PMID 30271655, 2018). "Besides, ILK expression and p62 accumulation were also increased in vastus muscle from old mice, indicating that the intracellular mechanisms elicited by hyperphosphatemia in myoblasts were also modified in vivo." (PMID 30271655, 2018).
Hypertension (3 papers, 2022 to 2024). The presence of chronic increased pressure in the systemic arterial system. "Interestingly, integrin-linked kinase (ILK) signaling has been implicated in hypertension-mediated organ damage." (PMID 36902363, 2023).
meningioma (3 papers, 2020 to 2023). A generally slow growing tumor attached to the dura mater. "Functional clustering analysis and literature mapping aided in understanding the potential role of integrin-linked kinase (ILK) in regulating the altered biological cascades in high-grade meningioma, interconnecting integrin binding, angiogenesis, proliferation, and apoptosis." (PMID 37887327, 2023). "Furthermore, proteome-level changes in EMO and integrin cell surface interactions were investigated in a high-grade meningioma (IOMM-Lee) cell line by inhibiting integrin-linked kinase (ILK)." (PMID 37887327, 2023). "The investigation of ILK inhibition using Cpd22 in a high-grade meningioma cell line (IOMM-Lee) showed a decrease in proliferation and angiogenesis followed by an increase of apoptosis." (PMID 37887327, 2023). "In this study, we validated the overexpression of ILK in high-grade meningioma using a MRM-based targeted proteomics approach." (PMID 37887327, 2023). "The enriched altered pathways highlight the role of ILK as a master regulator in high-grade meningioma tumorigenesis, regulating apoptosis, proliferation, and angiogenesis." (PMID 37887327, 2023). "FDA-approved drugs like oxypertine, pemigatinib, selpercatinib, and belumosudil showed encouraging results with high binding affinities and can be further explored for their inhibitory effects on ILK and treating high-grade meningioma." (PMID 37887327, 2023). "The administration of Cpd22 (ILK inhibitor) in a high-grade meningioma cell line (IOMM-Lee) provided evidence supporting the therapeutic potential of this kinase." (PMID 37887327, 2023). "The peak areas of peptides ITGB1 and ILK showed upregulation in high-grade meningioma when compared with control samples and low-grade meningioma." (PMID 37887327, 2023). "A study employing the inhibition of ILK showed that this affects cell growth in meningiomas by hindering the interaction of ILK with downstream components of PI3K-AKT." (PMID 32974197, 2020). "A previous study using meningioma cell lines reported the efficacy of ILK inhibition in meningiomas." (PMID 32974197, 2020). "Inhibiting the activity of ILK affected the levels of key proteins known to be key players in meningioma pathobiology namely EIF4G1, CSNK2A1, and several others." (PMID 32974197, 2020). "The inhibition of primary cell lines of meningioma with ILK inhibitor (Cpd22) was performed in meningioma patient-derived primary cell lines." (PMID 32974197, 2020). "The pathway coupling ILK to ECM matrix in high-grade meningioma unveils the potential that could be unleashed using belumosudil to treat high-grade meningioma." (PMID 37887327, 2023). "Meningioma has many unknown pathological mechanisms that can be discovered through in-depth molecular research; in that light, ILK inhibitors are indeed an integral research tool." (PMID 37887327, 2023). "For the identification of a potential adjuvant therapeutic adjunct in meningiomas where the tumor is either aggressive, recurrent or is unamenable to conventional surgery owing to tumor location; we have assessed the implication of ILK inhibition in meningioma cell lines." (PMID 32974197, 2020). "The in silico pathway analysis was followed by validation of integrin-linked kinase (ILK) along with its associated pathway components, like ITGB1 and VIM, which are known to play important roles in regulating the EMO and EMT transmission responsible for the progression of meningioma." (PMID 37887327, 2023). "ILK also coordinates epithelial–mesenchymal transition (EMT), which acts as a contributing factor in the metastatic and invasive nature of anaplastic meningioma." (PMID 37887327, 2023). "Future investigations might lead to unraveling the huge potential of ILK as a therapeutic target by taking these repurposed drugs along with reported inhibitors like QLT-0267 and OSU-T315 in the context of high-grade meningioma." (PMID 37887327, 2023).
meningioma (continued). "To determine the influence on inhibition of the ILK, one of the key components that regulate the three perturbed pathways namely Integrin, PI3K-Akt, and NF-κB, we have used the ILK inhibitor Cpd22 (Merck Millipore) on both meningioma patient-derived primary cell line as well as Ben-Men1." (PMID 32974197, 2020).
osteoporosis (3 papers, 2018 to 2025). A condition of reduced bone mass, with decreased cortical thickness and a decrease in the number and size of the trabeculae of cancellous bone (but normal chemical composition), resulting in increased fracture incidence. "This review summarizes that ILK can modulate the process of bone formation and is implicated in the development of osteoporosis." (PMID 40171447, 2025). "Additionally, the well-known pathophysiological processes that cause osteoporosis (such as ROS) can also modulate ILK, triggering downstream signaling to cause osteoporosis." (PMID 40171447, 2025). "Their research indicated that ILK may be related to osteoporosis because mutations in the ILK phosphate receptor site in the alpha (alpha NAC) transcriptional regulator can affect matrix gene expression and lead to osteopenia." (PMID 40171447, 2025). "While numerous studies have explored the relationship between ILK and bone metabolism, the precise role of ILK in osteoporosis remains elusive." (PMID 40171447, 2025). "If ILK is formulated as a new targeted therapy for osteoporosis, it will constitute a significant advancement in sustaining bone health." (PMID 40171447, 2025). "Since the current clinical drugs for osteoporosis are limited to promoting bone formation and resorption, it is necessary to clarify the specific function and molecular mechanism of ILK in type H vessels." (PMID 40171447, 2025). "Our research has revealed that the downregulation of ILK expression within the bone marrow microenvironment of osteoporosis patients offers novel insights into potential therapeutic targets for this condition." (PMID 40171447, 2025). "In line with the expression level of Periostin, ILK, pAkt and pGSK3β levels were also reduced in BMSCs derived from female rats with osteoporosis." (PMID 34591063, 2021). "The present role of ILK in the pathogenesis of osteoporosis is also described." (PMID 40171447, 2025). "From these studies, ILK is not only involved in the pathogenesis of primary osteoporosis and secondary osteoporosis, but also in the regulation of osteoporosis by mechanical stimulation, so there is a significant space for ILK to be discovered in the pathophysiology of osteoporosis." (PMID 40171447, 2025). "In the present study, we found that Periostin was reduced in BMSCs derived from the osteoporosis rat model and that overexpression of periostin could enhance the osteogenic ability of BMSCs, in part by activating the ILK/Akt/GSK3β axis." (PMID 34591063, 2021). "Strategies that target ILK may as a new prospective treatment for osteoporosis (OP)." (PMID 40171447, 2025). "Therefore, the role of ILK in osteoporosis therapy deserves our attention as well." (PMID 40171447, 2025). "Therefore, the decreased expression of ILK in the bone microenvironment of osteoporosis patients may lead to decreased osteogenic differentiation of BMSCs and promote adipogenesis, potentially contributing to bone mass loss." (PMID 40171447, 2025). "Therefore, it is worthwhile to explore whether there is a correlation between ILK and osteoporosis in postmenopausal women due to the decline of estrogen." (PMID 40171447, 2025). "Thus, ILK may play a role in the development of secondary osteoporosis." (PMID 40171447, 2025). "•ILK is involved in osteoporosis pathogenesis, and ILK-targeted therapies may emerge as a novel treatment for OP." (PMID 40171447, 2025).
pancreatic adenocarcinoma (3 papers, 2016 to 2023). "Overexpression of ILK was associated with the expression of the E-cadherin repressor Snail and N-cadherin in pancreatic adenocarcinoma." (PMID 27683053, 2016). "Three pathways including pancreatic adenocarcinoma signaling, ILK signaling and antiproliferative role of TOB in T cell signaling were enriched in GSE116347 MC38 tumor Treg." (PMID 34084175, 2021).
pulmonary hypertension (3 papers, 2016 to 2024). Increased pressure within the pulmonary circulation due to lung or heart disorder. "Indeed, in chronic hypoxia in pulmonary hypertension, decreased ILK expression is involved in regulating the vascular SMC phenotype." (PMID 37452166, 2023).
serous ovarian cancer (3 papers, 2021 to 2022). "High gene expression of ETAR/ILK/YAP/AP-1/ZEB1 was a strong predictor of poor clinical outcome in serous ovarian cancer patients, indicating the translational relevance of this signature expression." (PMID 35477522, 2022). "Furthermore, recent studies in serous ovarian cancer (SOC) indicate that ILK may function as a link between proteolytic and adhesive signaling, connecting ILK cytoskeletal dynamics and cell invasion processes mediated by invadopodia." (PMID 35804980, 2022).
squamous carcinoma (3 papers, 2006 to 2022). "In this study, we employed VS, based on the ILK protein structure, to find out two potential antiesophageal squamous cell carcinoma drugs, which are nilotinib and teniposide, and verified the binding ability of ILK protein with two compounds by surface plasmon resonance (SPR)." (PMID 36618074, 2022). "Moreover, QLT0267 did not reverse ILK-mediated radiosensitization of mutant FaDu cells (a human epithelial cell line from a squamous cell carcinoma of the hypopharynx) that were transfected with a constitutively active form of ILK." (PMID 30276218, 2018).
uremia (3 papers, 2022 to 2025). A clinical syndrome associated with the retention of renal waste products or uremic toxins in the blood. "Aortas extracted from WT and cKD-ILK mice were exposed to high doses of the uremic toxins pCS and IS (226 μg/mL and 100 μg/mL, respectively) for 24 h, to simulate uremia, and mRNA levels of ILK and fibrosis markers were analyzed." (PMID 41516093, 2025). "Finally, we observed that silencing ILK in vascular smooth muscle cells, which blunted the uremia-induced increase in its kinase activity, prevented the expression of fibrosis markers, suggesting a direct relationship between them." (PMID 41516093, 2025). "Recently, our group has demonstrated that ILK is required for the formation of podosomes, structures that mediate cell adhesion and migration of monocytes across ECM-based barriers, which cause dysfunction and vascular damage in the context of uremia." (PMID 38734696, 2024). "Therefore, uremia could probably be the reason why ILK expression is increased in circulating mononuclear cells during CKD." (PMID 38734696, 2024). "Taken together, these data suggest that ILK plays a prominent and essential role in podosome formation, ECM degradation and migration that might favor monocyte extravasation in uremia." (PMID 35246616, 2022).
viral infection (3 papers, 2013 to 2017). "Several pathways, most notably the Interferon signaling pathway and the EIF2 and ILK signaling pathways, were induced by virus infection." (PMID 25905045, 2015). "While ILK has been studied widely in cancer, its role in viral infections is poorly understood." (PMID 29085037, 2017). "However, in ILK mutant NCCs 48-h post-viral infection, there was a large accumulation of cortical actin in the cell cortex and a significant increase in short, randomized filapodia-like protrusions." (PMID 24131868, 2013).
aortic valve calcification (2 papers, 2022 to 2024). "We have previously demonstrated a link between decreased ILK expression in valve endothelial cells and aortic valve calcification in humans." (PMID 38534325, 2024). "Thus, we hypothesize that endothelial ILK plays a protective role in calcific aortic valve disease, preventing valve endothelial dysfunction and osteogenic cell differentiation in a nitric oxide-dependent manner." (PMID 36139812, 2022). "Thus, ILK might be a new therapeutic target in preventing aortic valve calcification during CAVD." (PMID 36139812, 2022).
aortic valve stenosis (2 papers, 2021 to 2022). Aortic valve stenosis (AVS) is a condition characterized by narrowing of the heart's aortic valve opening. "First, we analyzed the protein expression of ILK in human valve samples collected as surgical residues from patients with calcific aortic valve stenosis and age-matched non-CAVD controls." (PMID 36139812, 2022).
bladder (2 papers, 2020 to 2025). "Our data showed that the underactive bladder function was significantly improved in DCP rats intravenously treated with ILK gene-modified BMSCs compared to those in the DM, BMSCs, and Ad-null-BMSC group." (PMID 32650831, 2020).
cardiac ischemia (2 papers, 2023). "Genistein treatment (10−5 to 10−10 μmol) in an acute myocardial ischemia model, increased the endothelial colony-forming cell (ECFC) migration and proliferation, and parallel increased the expression of ILK, α-parvin, F-actin, and phosphorylation of ERK 1/2 signaling." (PMID 37275572, 2023).
Chronic colitis (2 papers, 2011 to 2023). A chronic inflammatory disease of the large intestine (colon, cecum and rectum). "We next investigated the impact of loss of ILK in epithelial cells in a model of chronic colitis, as this is considered to be more representative of human IBD." (PMID 21806815, 2011). "Since chronic colitis is a significant risk factor for development of CRC, we investigated whether myeloid-ILK deficiency ameliorates the colitis-associated cancer (CAC) model, also known as the AOM/DSS model." (PMID 38077324, 2023).
diabetic cardiomyopathy (2 papers, 2022 to 2024). Diabetic cardiomyopathy is a disorder of the heart muscle in people with diabetes. "Thus, liraglutide demonstrated a positive effect on diabetic cardiomyopathy in rats, potentially through the ILK-associated PI3K/AKT/PTEN axis." (PMID 38543160, 2024). "This study was aimed at obtaining conclusive evidence for the potential of liraglutide in mitigating diabetic cardiomyopathy via the modulation of the ILK/PI3K/Akt/PTEN signaling pathways." (PMID 38543160, 2024). "The aim of this study was to explore the role of ILK in an in vitro model of diabetic cardiomyopathy." (PMID 35571621, 2022). "Furthermore, low levels of cardiac ILK have been observed in an animal model of diabetic cardiomyopathy." (PMID 38543160, 2024). "Our findings suggest that liraglutide, through its targeting of GLP1Rs, affects the expression of ILK-related PI3K/AKT/PTEN, ultimately mitigating diabetic cardiomyopathy by regulating these signaling pathways." (PMID 38543160, 2024).
Ewing sarcoma (2 papers, 2006 to 2010). A small round cell tumor that lacks morphologic, immunohistochemical, and electron microscopic evidence of neuroectodermal differentiation. "The functional significance of ILK in malignancies is highlighted by the fact that ILK is overexpressed in several human tumours, including Ewing's sarcoma, primitive neuroectodermal tumour and medullablastoma." (PMID 16643659, 2006).
gestational diabetes (2 papers, 2022 to 2025). Carbohydrate intolerance first diagnosed during pregnancy. "Bioinformatics analyses also have expanded our understanding of ILK's role by showing that the ILK pathway, along with glycolysis and gluconeogenesis, is associated with biological processes linked to extracellular vesicles–associated microRNAs that undergo changes in gestational diabetes mellitus." (PMID 40272437, 2025).
glomerulosclerosis (2 papers, 2019). A hardening of the kidney glomerulus caused by scarring of the blood vessels. "In present study, the elevated expression of ILK in the kidney of lupus-prone mice decreased significantly after DZ2002 treatment, in parallel to the alleviation of proteinuria and glomerulosclerosis." (PMID 30696480, 2019).
Glucose intolerance (2 papers, 2016 to 2021). Glucose intolerance (GI) can be defined as dysglycemia that comprises both prediabetes and diabetes. "We find that depletion of integrin-linked kinase (ILK) in the pancreatic epithelial cells of mice results in glucose intolerance due to a loss of the intra-islet vasculature." (PMID 27995929, 2016). "To further describe the glucose intolerance and delayed insulin release observed in ILK cKO mice, we investigated whether the islet capillaries were perfused." (PMID 27995929, 2016).